MGMT (O-6-methylguanine-DNA methyltransferase)
Diseases named in the same sentence as MGMT in open-access papers (continued):
Sharing a sentence is not in itself a finding about the gene and the disease.
glioma (continued). "As a result, MGMT promoter methylation status has become the single most important prognostic factor in an era in which the vast majority of adults with glioma are treated with alkylating agent-based chemotherapy." (PMID 33293629, 2021). "Promoter methylation-mediated silencing of MGMT is associated with increased sensitivity towards temozolomide and present in the vast majority of IDH-mutant gliomas." (PMID 33216206, 2021). "MGMT hypermethylated gliomas are much more responsive to therapies with alkylating chemotherapeutics such as temozolomide (TMZ) than those without MGMT promoter hypermethylation." (PMID 33917711, 2021). "Pseudo-progression occurs in 15–50% of patients with gliomas particularly MGMT methylated and IDH mutant tumors undergoing standard therapy." (PMID 34676470, 2021). "MGMT promoter methylation was detected using methylation-specific PCR from genomic DNA extracted from the CSF of glioma patients, with higher sensitivity than from serum." (PMID 33919036, 2021). "Some factors that affect the prognosis of patients with high-grade glioma, such as age, histological type, single or multiple gliomas, extent of resection, MGMT methylation status, and Ki-67 level, were verified in our results." (PMID 35096561, 2021). "Molecular biomarkers like IDH status, MGMT promoter status, 1p19q, ARTX have been considered as glioma progression-associated marker." (PMID 34603309, 2021). "Our results confirmed the known influencing factors for OS of high-grade gliomas, such as age, histological type, number of gliomas, extent of resection, MGMT methylation status, etc.." (PMID 34055639, 2021). "For instance, a novel link between the Hh pathway and the O-6-methylguanine-DNA-methyltransferase (MGMT) repair mechanism in conferring glioma cells TMZ resistance has been reported in several studies." (PMID 34638233, 2021). "Much of the MGMT transcriptional studies and its negative regulation in gliomas are heavily related to the promoter methylation, however, the regulatory elements elsewhere in the gene have received scant attention." (PMID 33801310, 2021). "According to the clinical information and risk model score of patients with glioma, a nomogram model was established to predict the prognosis of patients, including age, PRS type, grade, IDH, 1p19q, MGMT status, and risk score." (PMID 34123852, 2021). "Future development of novel chemotherapeutic agents targeting CDKN2A alternation would be a promising approach not only for IDH‐mutant gliomas but also for GBMs with unmethylated MGMT." (PMID 33838014, 2021). "In C6 glioma cells implanted intracranially in rats, our group recently described the capacity of mifepristone to reduce the expression of the MGMT protein." (PMID 33680961, 2021). "The molecular mechanism underlying the process indicated that RIP2 can activate the NF‐κB signaling pathway and upregulate the expression of O6‐methylguanine‐DNA methyltransferase (MGMT), following which the glioma cells develop drug resistance." (PMID 33460245, 2021). "Several identified genetic and/or transcriptional indicators including IDH mutation, O-6-methylguanine-DNA methyltransferase (MGMT) promoter methylation, and 1p/19q co-deletion were found to be closely related to glioma prognosis." (PMID 34659549, 2021). "MGMT unmethylated glioma with higher CI also showed better prognosis than with lower CI samples (p value < 0.0001)." (PMID 34070840, 2021). "Histological grades, IDH mutation 40, 41, MGMT methylation 42-44 and EMP3 expression 31-33 were all validated prognostic factors of glioma." (PMID 34335936, 2021). "Neither in vivo nor in vitro, however, the presence and possible importance of the MGMT gene in dogs' glioma treatment response or progression pattern have been investigated up to date." (PMID 34477324, 2021). "The methylation status of the MGMT gene promoter controls MGMT protein expression and, therefore, the response of gliomas to alkylating chemotherapy agents." (PMID 32542524, 2021).
glioma (continued). "For human glioma, IDH mutation, chromosome 1p/19q co-deletion and MGMT promoter methylation are pivotal biomarkers for the guidance of glioma prognostication and treatment." (PMID 33509092, 2021). "In conclusion, in the tested canine glial tumour cell lines, temozolomide was additive to the effects of irradiation in clonogenic cell survival assay and MGMT promoter was highly methylated." (PMID 34477324, 2021). "They found that these combined modalities were able to differentiate glioma grade (AUC 0.852), ATRX mutation (AUC 0.851), MGMT mutation (AUC 0.757), IDH1 mutation (AUC 0.887), and 1p19q codeletion (AUC 0.978)." (PMID 34194287, 2021). "O6-methylguanine-DNA methyltransferase (MGMT) promoter methylation predicts good response to temozolomide (TMZ)-based chemotherapy in glioma patients." (PMID 34257545, 2021). "Our results are consistent with previous results on the effect of MGMT on the prognosis of patients with glioma." (PMID 34814870, 2021). "Promoter methylation of the O-6-Methylguanine-DNA Methyltransferase (MGMT) gene is a prognostic marker in patients with glioma because MGMT methylation leads to better response to alkylating agents, such as TMZ." (PMID 34178638, 2021). "It is well known that the MGMT promoter methylation status is a key biomarker indicating temozolomide (TMZ) chemotherapy sensitivity in gliomas." (PMID 34912807, 2021). "Previous study has shown STAT3 inhibition overcomes TMZ resistance by reducing MGMT expression in glioma." (PMID 34291563, 2021). "Promoter methylation of the O6−methylguanine DNA methyltransferase (MGMT) gene is mainly investigated in glioma." (PMID 34281602, 2021). "Tumors of the newly identified group demonstrate the highest frequency of an unmethylated MGMT promoter among all IDH-mutant gliomas (61.3%, 19/31)." (PMID 33216206, 2021). "This study was, to our knowledge, the first to analysis perfusion parameters evaluated by combining IDH mutation status and MGMT methylation status and TERT mutation status in glioma gene detection results." (PMID 34814870, 2021). "Promoter methylation of MGMT has been well known as a valuable prognostic factor and predictor of response to temozolomide for glioma." (PMID 34544433, 2021). "Analysis of PD-L1 expression and MGMT promoter methylation showed higher PD-L1 expression in MGMT methylated glioma (n = 26) compared to MGMT unmethylated glioma (n = 23, p > 0.05)." (PMID 33963441, 2021). "It was also found that AEBP1 expression was overexpressed in IDH wild type glioma patients and MGMT promoter unmethylation-type glioma patients." (PMID 34373835, 2021). "In TCGA dataset, patients in cluster 1 were mainly with younger age, lower grade of glioma, IDH mutated, MGMT promoter methylated, 1p/19q co-deleted and enriched in Neural and Proneural subtypes." (PMID 34307339, 2021). "In the TMZ‐resistant glioma cell xenograft model, inhibition of NF‐κB and MGMT enhances the response of the transplanted tumor to TMZ." (PMID 33460245, 2021). "Low SAA1 expression segregated glioma patients who were treated with Temozolomide (TMZ) or with high MGMT promoter methylation into survival groups in TCGA and CGGA dataset." (PMID 33854635, 2021). "The mechanism of TMZ resistance reported so far is related to the heterogeneity of glioma cells, upregulation of O6-methylguanine DNA methyltransferase (MGMT), DNA repair, and signal transducer and activator of transcription 3 (STAT3)." (PMID 33614649, 2021). "All those results suggested that CDHR1 was associated with IDH mutation and MGMT methylation, and CDHR1 was an important prognostic factor of glioma." (PMID 34335936, 2021). "Many studies have shown a correlation between MGMT protein expression in gliomas and the methylation level of the promoter region, which is usually about 30 to 60%." (PMID 34201219, 2021).
glioma (continued). "We did not observe significant difference of SCG3 expression between gliomas grouped by other common genetic features in gliomas, such as TERT promoter mutations and MGMT promoter methylation." (PMID 34257545, 2021). "Univariate analysis showed that the level of PTPRN, MGMT, VEGF and WHO grade were associated with the prognosis of glioma patients." (PMID 34557405, 2021). "Multiple studies have shown that glioma patients with MGMT promoter methylation are more sensitive to chemotherapy and their survival time is longer than those without methylation." (PMID 34026352, 2021). "In summary, we have demonstrated that METTL3 promotes the TMZ resistance of glioma cells by increasing MGMT and ANPG in an m6A-dependent manner." (PMID 34336690, 2021). "The relation between MGMT promoter methylation and AEBP1 expression was also analyzed, and the result showed that the expression of AEBP1 was higher in MGMT promoter unmethylated glioma patients." (PMID 34373835, 2021). "Hypermethylation of the MGMT promoter is in general a typical feature of IDH-mutant gliomas, except the recently described subtype of infratentorial IDH-mutant astrocytomas." (PMID 33216206, 2021). "PET-based radiomics is also a promising method to noninvasively evaluate the MGMT status of gliomas." (PMID 34295824, 2021). "Specifically, histological results in our study also indicated that OEF values (r = 0.42, p = 0.002) or less relevant Ktrans values (r = 0.39, p = 0.005) were positively correlated with the cell cycle marker Ki67, but only in MGMT unmethylated gliomas." (PMID 34671241, 2021). "The results showed that except for sex, there were significant differences in age, glioma type, IDH mutation status, ATRX mutation status, 1p/19q status, MGMT promoter methylation status, and survival status between the high- and low-risk groups." (PMID 34136486, 2021). "The MGMT promoter methylation status can predict response to temozolomide, a common chemotherapeutic drug for glioma, in patients with glioma." (PMID 34070840, 2021). "An important molecular property in gliomas bearing great prognostic relevance is the Oxygen 6-methylguanine DNA methyltransferase (MGMT) promotor methylation status." (PMID 33857203, 2021). "Temozolomide is the only first-line drug in the treatment of recurrent glioma, and the levels of DNA repair gene O6-methylguanine DNA methyltransferase (MGMT) indicated sensitivity to the drug." (PMID 34326872, 2021). "In contrast to the majority of IDH-mutant gliomas, more than 60% of the samples in our cohort presented with an unmethylated MGMT promoter." (PMID 33216206, 2021). "Low CALD1 expression indicates worse survival outcome both in the MGMT methylated (p value < 0.001) and MGMT unmethylated (p value < 0.001) glioma." (PMID 34070840, 2021). "Analysis of MGMT promoter methylation revealed higher PD-L1 expression in MGMT methylated glioma (mean amounts of 30%) compared with MGMT unmethylated glioma (mean amounts of 26%)." (PMID 33963441, 2021). "In our cohort, the MGMT promotor was methylated in 92% (97/106) and unmethylated in 8% (9/106) of the tumors classified as glioma IDH-mutant." (PMID 33941250, 2021). "Hypermethylation of the MGMT (O6-methylguanine-DNA methyltransferase) promoter is considered an important predictor of a good response to chemotherapy with temozolomide (TMZ) in glioma patients." (PMID 33916593, 2021). "Despite its primary efficiency in glioma treatment, drug resistance is inevitable in patients with high O6-methylguanine-DNA methyltransferase (MGMT)." (PMID 34568018, 2021).
glioma (continued). "Given the well-established role Wnt signaling plays in gliomas, several therapeutic approaches have been investigated that target this signaling pathway, specifically those that modulate MGMT expression." (PMID 34337348, 2021). "Wei and colleagues found that the fusion radiomics signature (clinical factors and texture features) showed great performance for predicting MGMT promoter status of glioma, with an AUC value of 0.902 in the validation cohort." (PMID 34295824, 2021). "MGMT was initially identified as a prognostic and predictive signature for glioma diagnosis in patients treated with temozolomide." (PMID 34336645, 2021). "Subsequently, the radiomics signatures were utilized to predict the genetic profile of ATRX, IDH1/2, MGMT and 1p19q co-deletion, as well as differentiating low-grade glioma from high-grade glioma." (PMID 34944806, 2021). "To study the role of MGMT in canine glial tumour cell lines in response to treatment, we measured the levels of MGMT methylation in the three canine cell lines." (PMID 34477324, 2021). "The degree of MGMT promoter methylation was compared with that in healthy controls as well as in hypermethylated gliomas." (PMID 33917711, 2021). "Addition of MR diffusion to conventional MRI features provides added diagnostic value in preoperative determination of IDH1, MGMT, and ATRX in patients with glioma." (PMID 34056604, 2021). "The prognostic and predictive role of MGMT methylation is well known in high-grade gliomas treated with temozolomide, but hypermethylation seems to be also related to anti-VEGF treatment." (PMID 34081269, 2021). "We have reported that combinations of methylation at 4 or more CpG sites have equivalent predictive value for MGMT expression in gliomas and TMZ therapy response in GBM31." (PMID 33628600, 2021). "The IDH mutation frequency (94% and 16%, respectively) and MGMT methylation frequency (61% and 38%, respectively) of grade III and grade IV glioma reported in our study were consistent with the frequency reported in the past." (PMID 35096561, 2021). "Considering the relevant molecular determinants for glioma from the new WHO brain tumor classification, IDH status was characterized in 83.4% (121/145) of all glioma cases and MGMT in 82.6% (90/109) of high-grade gliomas." (PMID 32951126, 2021). "Using samples from Xiangya hospital, we found the consistent results that glioma patients with histological type of astrocytoma, wild-type IDH1, and unmethylated MGMT had higher risk scores." (PMID 34805164, 2021). "In glioma, hypomethylated MGMT promoter indicates the additional survival benefit from alkylation agent temozolomide." (PMID 33717678, 2021). "The root mean square and variance features from CBVa histogram and contrast-enhancing component of the tumor location from structural imaging enable the iVASO-CBVa to evaluate the MGMT methylation status in gliomas." (PMID 34422648, 2021). "Further, an enforced NRF2 expression markedly augmented the MGMT mRNA and protein levels in glioma cells." (PMID 33801310, 2021). "The alkylating drug TMZ is routinely used for chemotherapy in glioma patients and MGMT promoter status was identified as a useful predictive biomarker for TMZ efficacy." (PMID 33936093, 2021). "The findings offer novel insight into the regulation of MGMT transcription in glioma and other cancer types." (PMID 34201219, 2021). "A consensus has been reached that the MGMT methylation is closely related to the prognosis, sensitivity to chemoradiotherapy, and treatment decision-making in glioma patients." (PMID 34281602, 2021). "The MGMT unmethylation glioma patients have higher rCBF in our study, which means the MGMT unmethylation glioma patients have more blood supply and faster blood flow in the tumor area." (PMID 34814870, 2021).
glioma (continued). "In MGMT methylated glioma from the TCGA dataset, high CI samples manifested better survival outcome than low CI samples (p value = 0.0013)." (PMID 34070840, 2021). "Accordingly, we confirmed that RIP2 induces MGMT expression in glioma cells through the NF‐κB pathway." (PMID 33460245, 2021). "With the development of genetics and molecular biology, many molecular biomarkers have been developed for gliomas, such as IDH mutation, ATRX mutation, MGMT methylation status, and 1p/19q status, but they have limitations." (PMID 34136486, 2021). "In light of the genetic characteristics, gliomas can be divided into Isocitrate dehydrogenase (IDH) mutation and O-6-methylguanine-DNA methyltransferase(MGMT) methylation." (PMID 34026352, 2021). "The 1p/19q non−codel, IDH-wildtype, classical and mesenchymal subtype, MGMT promotor unmethylated, and higher WHO grade, which are the malignant clinicopathological features in glioma, were associated with a higher risk score." (PMID 34336837, 2021). "In fact, integration of IDH mutation and MGMT promoter methylation status, together with application of molecular information derived from several “-omics” approaches, may have the potential to substantially improve the classification and prognostication of gliomas." (PMID 33673213, 2021). "The demethylation of the MGMT in glioma leads to tumor cell resistance to alkylating agents such as temozolomide." (PMID 34121368, 2021). "CBVa obtained from iVASO MRI can identify the difference of tumor histogram and structural features between MGMT methylation gliomas and unmethylation ones." (PMID 34422648, 2021). "When considering only biopsies performed after 2015, after introduction of the revised WHO classification, IDH was obtained in 96.9% (94/97) and MGMT in 92.8% (64/69) of high-grade glioma cases." (PMID 32951126, 2021). "The purpose of this in vitro cell culture study is to test the response of canine glial tumour cells towards temozolomide, radiotherapy and combination of both, as well as to investigate the potential involvement of MGMT in the mechanism of sensitization." (PMID 34477324, 2021). "For all glioma patients or those who received chemotherapy, MGMT promoter methylated patients with AEG-1 low expression had a survival advantage compared with unmethylated ones." (PMID 34462446, 2021). "The lower the expression of MGMT in glioma patients, the better the chemotherapy effect of temozolomide." (PMID 34556022, 2021). "TMZ‐resistant glioma xenograft models were established to evaluate the role of the RIP2/NF‐κB/MGMT signaling pathway in drug resistance." (PMID 33460245, 2021). "Although various biomarkers related to gliomas are used in clinical practice, such as O6-methylguanine-DNA methyltransferase (MGMT) and osteopontin (OPN), their sensitivity and specificity are debated." (PMID 34976781, 2021). "In terms of clinical characteristics, we found that grade II glioma patients, as well as patients with the IDH mutation, 1p/19q codel, and methylated MGMT promoter were more likely to be in the low immune risk score group." (PMID 34623790, 2021). "Implications of MGMT promotor status and other molecular markers on outcome warrants further evaluation in prospective cohorts of glioma WHO grade II which have been treated with uniform therapeutic approaches." (PMID 33184319, 2020). "This proposed pipeline not only saves the time in tumor annotation and avoids interrater variability in glioma segmentation but also achieves good prediction of MGMT methylation status." (PMID 33029531, 2020). "The assessment of both mutation status and gene expression, such as O6-methylguanine-DNA-methyltransferase (MGMT) gene expression or isocitrate dehydrogenase (IDH) mutation, is essential for predicting therapeutic responses when treating gliomas." (PMID 33746649, 2020). "Glioma cases were analyzed for IDH1/2 mutations and MGMT promoter methylation by DNA sequencing and methylation-specific PCR, respectively." (PMID 33552543, 2020).